MIR6843 (microRNA 6843)
Synonyms: hsa-mir-6843
Gene: MicroRNA gene on chromosome 8 (27,610,601 to 27,610,751, reverse strand). Ensembl gene ENSG00000284280.
Diseases named in the same sentence as MIR6843 in open-access papers:
MIR6843 is named in the same sentence as 1 disease in open-access papers, as found by Europe PMC text mining. Sharing a sentence is not in itself a finding about the gene and the disease.
MIR6843 shares sentences with these, for which no sentence is quoted: Alzheimer disease (1 paper).